ACE (angiotensin I converting enzyme)
Diseases named in the same sentence as ACE in open-access papers (continued):
Sharing a sentence is not in itself a finding about the gene and the disease.
Hypercalcemia (54 papers, 2007 to 2025). An abnormally increased calcium concentration in the blood. "Lab parameters in our patient including elevated 1,25 dihydroxyvitamin D, ACE level, and suppressed iPTH support his granulomatous load as the cause of hypercalcemia." (PMID 18687121, 2008). "This made the diagnosis of tuberculosis less likely, especially in the context of sudden-onset ventricular fibrillation (cardiac involvement) with hypercalcemia, elevated ACE levels, hilar lymphadenopathy, and a skin rash with vague constitutional symptoms." (PMID 40988789, 2025). "Laboratory findings characteristic of sarcoidosis, including elevated ACE levels, hypercalcemia, and systemic symptoms such as fatigue, were frequently observed—paralleling the case we described." (PMID 40927193, 2025). "Initial laboratory investigations indicated systemic inflammation, with a mildly elevated serum angiotensin-converting enzyme (ACE) level, hypercalcemia, and increased urinary calcium excretion." (PMID 40927193, 2025). "Elevated ACE levels and 1,25 Vitamin D with hypercalcemia can support the diagnosis but are unnecessary." (PMID 41209849, 2025). "These include angiotensin-converting enzyme (ACE) inhibitors, statins, antibiotics, bile acid sequestrants, proton pump inhibitors (PPIs), corticosteroids, laxatives, thiazide diuretics (which may cause hypercalcemia but are also associated with vitamin D depletion), and lipase inhibitors." (PMID 41515142, 2025). "The combination of hypercalcemia, elevated ACE, inflammation and newly enlarged mediastinal lymphadenopathies is consistent with a flare-up of the sarcoid-like reaction, likely provoked by the dual immune checkpoint inhibition." (PMID 40689241, 2025). "With evidence of systemic granulomas on CT abdomen in the liver and spleen, hypercalcemia, elevated ACE levels, and neurological involvement, neurosarcoidosis was considered as a possible diagnosis." (PMID 39391405, 2024). "Further evaluation of hypercalcemia showed a suppressed fasting parathyroid hormone level of 8.45 pg/mL and an elevated ACE level of 80 U/L." (PMID 39391405, 2024). "The laboratory tests showed isolated lymphopenia, slight hypercalcemia, normal serum protein electrophoresis, and elevated ACE and lysozyme." (PMID 36672683, 2023). "Laboratory investigations typically probe for elevated serum angiotensin converting enzyme (ACE), hypercalcemia, cerebrospinal fluid (CSF) abnormalities (e.g., elevated protein), pleocytosis, or increased ACE, IgG index, and T lymphocyte CD4+/CD8+ ratios." (PMID 37085608, 2023). "This can be followed by other investigations like tissue biopsies, serum angiotensin-converting enzyme (ACE) levels, serum protein electrophoresis, etc., to study the specific cause of hypercalcemia." (PMID 37900460, 2023). "Bilateral hilar adenopathy, the presence of skin lesions, uveitis, and laboratory tests such as hypercalcemia and increased ACE in the serum represent elements that can be found in the picture of both conditions." (PMID 36672683, 2023). "Five patients (41.6%) had elevated ACE, four patients (33.3%) had hypercalcemia, and eight (66.6%) had polyclonal hypergammaglobulinemia." (PMID 36619642, 2022). "Laboratory findings like hypercalcemia and elevated angiotensin-converting enzyme (ACE) levels can also be seen as the only presentation." (PMID 34540380, 2021). "DISR can be associated with typical sarcoid-like manifestation including bilateral hilar lymphadenopathy, uveitis, hypercalcemia, cutaneous lesions, elevated serum ACE levels, and FDG uptake on PET scans." (PMID 33505980, 2020). "In fact, hypercalcemia and increased serum ACE levels have also been described in patients with lymphoma." (PMID 26579198, 2015). "Laboratory investigations such as elevated serum angiotensin-converting enzyme (ACE), hypercalcemia, and hypercalciuria may provide supportive evidence, though they lack specificity." (PMID 40741038, 2025).
Hypercalcemia (continued). "Hypercalcemia and increased ACE occurred in similar proportions in the two groups." (PMID 39279263, 2024). "Serum ACE level was elevated in 238 of 674 patients (35%, 95% CI 32–39%), erythrocyte sedimentation rate was elevated in 64 of 202 patients (32%, 95% CI 25–38%), and hypercalcemia was present in 19 of 222 evaluated patients (9%, 95% CI 5–12%)." (PMID 27846819, 2016). "Finally it was only the synopsis of the clinical manifestations, the pathologic lab tests (hypercalcemia, ACE, IL-2-Receptor, lysozyme) and finally the response to treatment with steroids which allowed to confirm the diagnosis." (PMID 18053167, 2007). "Accordingly, it is judicious to advise patients with elevated s-ACE and HLA-DRB1*04 carriage to avoid excessive exposure to the sunlight as well as to monitor them for hypercalcemia especially during the light period of the year." (PMID 39939699, 2025). "Angiotensin-I-converting enzyme (ACE) serum levels were elevated in 2/10 (20%) cases and hypercalcemia was found in 1/8 (12%) cases." (PMID 37176720, 2023). "Evaluation of the hypercalcemia revealed the following: PTH < 3 (11–67 pg/mL), 25-hydroxyvitamin D 23.8 (30–95 ng/mL), 1,25-dihydroxyvitamin D 79 (18–72 pg/mL), and angiotensin converting enzyme (ACE) level 82 (9–67 U/L)." (PMID 26904327, 2016). "However, the increased ACE serum activity and the finding of granuloma formation by epithelioid histiocytes may suggest that these activated lymphoma-neighboring histiocytes may also be contributing to our patient’s hypercalcemia." (PMID 26425574, 2013). "In this case, the patient's combination of atypical findings (hypercalcemia, elevated vitamin D, splenomegaly, and high ACE level) in the absence of classic systemic or pulmonary symptoms ultimately warranted a kidney biopsy." (PMID 40964550, 2025). "Elevated serum angiotensin-converting enzyme (ACE) levels and hypercalcemia may provide supportive evidence, though these findings are nonspecific." (PMID 39416579, 2024). "Lab analysis revealed a negative thrombophilia and autoimmune panel, reduced levels of angiotensin-converting enzyme (ACE), no hypercalcemia, and no hypercalciuria." (PMID 38347580, 2024). "Additional laboratory tests, including angiotensin-converting enzyme (ACE), liver function, and hypercalcemia, were negative." (PMID 29671151, 2018). "Other etiologies of acute PTH-independent hypercalcemia were investigated by measuring serum angiotensin-converting enzyme (ACE) activity as a nonspecific marker for granulomatous-inflammatory diseases, and PTH-related peptide (PTHrP) for ruling out hypercalcemia of malignancy." (PMID 39906901, 2025).
cognitive decline (53 papers, 2005 to 2026). "Genetic analysis revealed a significant association between cognitive decline and polymorphisms in the ACE and PON1 genes." (PMID 40283626, 2025). "For example, in a cohort study including community-dwelling older adults with mild to moderate AD, the use of ACE inhibitors (ACEi) was associated with a slower cognitive decline, independent from their antihypertensive effects." (PMID 37784209, 2023). "Centrally acting angiotensin-converting enzyme (ACE) inhibitors are associated with reduced rates of cognitive decline in patients with established AD, independent of blood pressure reduction." (PMID 31083442, 2019). "Including data from over 850,000 individuals in 30 studies, ARBs were associated with less cognitive decline and were significantly better than either diuretics, beta blockers or angiotensin converting enzyme (ACE) inhibitors." (PMID 29543776, 2018). "ACE D-allele may be a genetic risk factor for cognition which increased serum ACE levels, and ACE inhibitor is a protective factor against cognitive decline." (PMID 37925455, 2023). "While some research indicates that the use of ACE-Is (or angiotensin receptor blockers) in older adults with AD is associated with a slower rate of cognitive decline, other research cautions in the use of ACE inhibitors as they may interfere with Aβ clearance." (PMID 29176997, 2017). "However, similar-sized studies have been sufficient to demonstrate an association between ACE D allele and cognitive decline in the elderly, and power calculations suggested we had enough patients to demonstrate at least a trend." (PMID 15725359, 2005). "However, the impact of RAS and the variability in its genes on cognitive decline in PD may be indirect, influencing the risk of cerebral hyperintensities or the impact of antihypertensive treatment with ACE inhibitors." (PMID 34302265, 2021). "Findings from the ONTARGET/TRANSCEND trials revealed that the use of angiotensin-converting enzyme (ACE) inhibitors or ARBs contributed to the reduction of albuminuria and a decrease in cognitive decline among individuals with CKD." (PMID 40979705, 2025). "ACE and REN, while central to cardiovascular regulation, have been linked to cognitive decline through RAS dysregulation in the brain." (PMID 40699836, 2025). "The same conclusion was also replicated in humans where ACE inhibitors delayed the onset of cognitive decline." (PMID 39766777, 2024). "Ohrui’s randomised, prospective, parallel group trial of 183 patients similarly found that ACE inhibitors reduced the rate of cognitive decline in patients with AD." (PMID 37627038, 2023). "Despite age being a major contributor to cognitive decline and disease pathology in AD, we have only limited information regarding age-related changes in brain ACE-1 and ACE-2." (PMID 35396835, 2022). "A clear example is the angiotensin-converting enzyme (ACE), which degrades Aβ, and ACE inhibitors that contribute to slow down cognitive decline." (PMID 29301387, 2018). "Here, we focused on bovine casein-derived peptide CH-3, which has a strong ACE inhibitory effect, and demonstrated that administration of CH-3 prevented cognitive decline in AD model mice, with a reduction of inflammation and oxidative stress." (PMID 28158298, 2017). "Secondary prevention for VaD, for example using angiotensin-converting enzyme (ACE) inhibitors, can significantly prevent further strokes and subsequent cognitive decline." (PMID 24252204, 2013). "Clinical evidence indicates beneficial effects of long-term antihypertensive treatment with a centrally active ACE inhibitor regarding retardation of the onset of cognitive decline." (PMID 23959119, 2013). "Controversially, these findings imply that the inhibition of ACE abolishes ACE-dependent clearance of β-amyloid, and hence the cognitive decline may be worsened." (PMID 37630190, 2023).
cognitive decline (continued). "Moreover, patients affected by cardiovascular disease show enhanced activity of brain ACE and ACE inhibitors ameliorate cognitive decline in the elderly." (PMID 34827650, 2021). "Interestingly, ACE overexpression in monocytes, migrating to the brain was shown to prevent AD cognitive decline." (PMID 29765306, 2018). "Moreover, angiotensin converting enzyme (ACE) inhibitors and AngII antagonists prevent cognitive decline in a chemically induced mouse model of HD and in models of AD." (PMID 28596754, 2017). "Similarly to previous reports, we also confirmed that an ACE inhibitor, perindopril, reduced the cognitive decline in AD mice." (PMID 28158298, 2017). "Furthermore, many researchers have suggested that some ACE inhibitors and Ang II receptor blockers (ARBs) have a beneficial effect to prevent cognitive decline in AD model mice." (PMID 28158298, 2017). "Finally, patients treated with ACE inhibitors such as Benazepril have a slowed cognitive decline." (PMID 40026671, 2025). "A previous study has already shown that blood pressure regulators that penetrate the brain are associated with protection against cognitive decline but others could not support the positive effect of centrally active ACE inhibitors on cognitive functions." (PMID 36361252, 2022). "The classical renin–angiotensin system (RAS), known as the angiotensin (Ang)-converting enzyme (ACE)/Ang II/Ang II type 1 (AT1) receptor axis, induces various organ damages including cognitive decline." (PMID 28721275, 2016). "Finally, we investigated the effect of MKP, which accounts for the main ACE inhibitory effect of CH-3 and has the possibility to penetrate the BBB, on cognitive decline induced by ICV injection of Aβ1–42." (PMID 28158298, 2017). "Although experimental evidence also indicated beneficial effects of a brain-penetrating ACE inhibitor on prevention of cognitive decline, the effect of central ACE inhibition on brain Aβ deposition is not clear." (PMID 23959119, 2013). "Those AD protective effects of ACE inhibitors led to the hypothesis that brain-penetrating ACE inhibitors could exert protection against cognitive decline independent of blood pressure lowering." (PMID 23959119, 2013).
Granuloma (53 papers, 2007 to 2026). A compact, organized collection of mature mononuclear phagocytes, which may be but is not necessarily accompanied by accessory features such as necrosis. "Angiotensin-converting enzyme (ACE) reflects the presence of granuloma; accordingly, serum ACE (sACE) and tubular injury markers are measured in renal sarcoidosis (RS)." (PMID 41632220, 2026). "Whole body PET scan confirmed extrapulmonary granulomas in some patients with lower immunoreactivity towards anti-ACE mAbs." (PMID 35996109, 2022). "In sarcoidal granulomas the increased ACE activity is predominately contributed by epithelioid cells and macrophages of the granuloma, and a higher serum level of ACE is observed in a majority of patients." (PMID 32508938, 2020). "ACE is secreted by epithelioid cells and macrophages and is thus a marker for the general burden of granulomas." (PMID 26799486, 2016). "Early evidence for this came from the analysis of ACE expression by the macrophages and giant cells found in granuloma." (PMID 27018193, 2016). "A clinical study evaluated the relation between the extent of granuloma infiltration using an x-ray score and the amount of serum TNFα, IL-6, IL-10, IL-12, angiotensin converting enzyme (ACE), and chitotriosidase (CTO)." (PMID 25180094, 2014). "In presented case, when pulmonary symptoms and granulomas appear again, it may be useful to monitor the changes in ACE and sIL-2R levels and consider the use of immunosuppressive agents if the pulmonary lesions worsen." (PMID 38933100, 2024). "Experimental studies have shown that ACE is upregulated in macrophages inside granulomas and that inhibiting the level of ACE in Schistosoma mansoni granulomas reduces the size of granulomas, indicating that ACE plays a potential role in the formation and maintenance of granulomas." (PMID 35615369, 2022). "ACE is upregulated in many immunological diseases, such as granuloma." (PMID 32508938, 2020). "Thus, there is an association between the immune activation of the monocytic-derived cells in a granuloma and ACE expression." (PMID 27018193, 2016). "A new parameter that we have established–ACE immunoreactivity (with mAb 9B9)—allowed us to detect 22 patients with decreased values (< 80%) of this parameter, which may indicate the presence of ACE in the blood that originates from macrophages/dendritic cells of granulomas." (PMID 35996109, 2022). "Previous reports of ACE expression within human Mtb granulomas led us to investigate whether ACE is also expressed within distinct MΦ populations in other types of intracellular bacterial granulomas similar to what we observed in our murine granuloma model with persistent STm infection." (PMID 36608122, 2023). "There were non-caseating granulomas in four different body sites, an infectious work-up was negative, radiographic evidence of bilateral hilar lymphadenopathy, and an elevated ACE level and panuveitis of the left eye." (PMID 33923240, 2021). "A video-assisted thoracoscopic surgery (VATS) lung biopsy showed non-caseating granulomas, and serum angiotensin converting enzyme (ACE) was elevated consistent with a diagnosis of pulmonary sarcoidosis." (PMID 30519468, 2018). "In conclusion, our results suggest that the presence of noncaseating granulomas on skin biopsy along with BAL lymphocytosis, a high CD4/CD8 ratio, and an elevated serum ACE level are associated with progressive disease." (PMID 23521826, 2013). "ACE levels have also been reported to be abnormally elevated in CVID patients without granulomas." (PMID 39359743, 2024). "However, his delayed presentation of calcinosis cutis, an increase in angiotensin-converting enzyme (ACE) level, and the biopsy of the palm lesion with noncaseating granulomas helped us reach the diagnosis." (PMID 39286669, 2024).
Granuloma (continued). "Our single-cell transcriptomics and functional characterization demonstrate that ACE expression specifies a MΦ population that has distinctive cellular features, functional properties, and TNF regulation compared to other types of MΦs in STm granulomas and infected spleens." (PMID 36608122, 2023). "While elevated serum levels of angiotensin-converting enzyme (ACE) and vitamin D, in conjunction with non-caseating granulomas on biopsy, are suggestive, they lack specificity, mandating the exclusion of alternative diagnoses such as rheumatoid arthritis and fungal infections." (PMID 39287657, 2025). "Further, ACE levels can be elevated in the setting of certain infections such as the human immunodeficiency virus (HIV) and other infections presenting with non-caseating granulomas such as histoplasmosis." (PMID 39359743, 2024).